ACAT1 (acetyl-CoA acetyltransferase 1)
Diseases named in the same sentence as ACAT1 in open-access papers (continued):
Sharing a sentence is not in itself a finding about the gene and the disease.
infection (12 papers, 2014 to 2025). The state of being infected such as from the introduction of a foreign agent such as serum, vaccine, antigenic substance or organism. "However, 25HC’s ability to protect against infection by Listeria monocytogenes was completely lost in ACAT1-deficient mice." (PMID 36695568, 2023). "The increased accessible PM cholesterol in ACAT1 KO cells did not affect invasion or cell-to-cell spread of Listeria as similar levels of infection were observed in both WT and ACAT1 KO cells after 22 hr." (PMID 36695568, 2023). "ACAT1 is a cholesterol regulatory enzyme, and many viruses rely on cholesterol for effective infection." (PMID 37511286, 2023). "In summary, in the present study, we explored the regulatory roles of ABC-transporters and ACAT1 in cholesterol metabolism of bovine macrophages in response to an infection of Mycobacterium bovis vaccine stain BCG." (PMID 32397995, 2020). "A closer look at individual proteins in the fatty acid metabolism pathway showed that acetyl-CoA acetyltransferase (ACAT1) exhibited increased TED values as the infection progressed." (PMID 32041945, 2020). "Accordingly, the least ABCG1, ABCA1 and ACAT1 proteins in BCG-infected RAW264.7 cells were found at 12 h post infection, while the least ABCA5 and ABCA6 were at 24 h post infection." (PMID 32397995, 2020). "Compared to mock-infected cells at day 1 post-infection, C. burnetii infection upregulated the expression of genes acat-1, acat-2, fabp-4 and apoE by more than 1.2 fold." (PMID 29390006, 2018). "Compared to wild-type cells, C. burnetii growth in acat-1-/- cells increased 2-fold at 4 days post-infection, indicating that blocking sterol esterification favors C. burnetii growth." (PMID 29390006, 2018). "Moreover, infection levels were similar in the ACAT1 KO cells that stably expressed either hACAT1(WT) or inactive hACAT1(H460A)." (PMID 36695568, 2023). "We propose that ACAT1 can act to restrict the rate of lipogenesis during infection." (PMID 32041945, 2020). "Besides, PPARγ, some of the critical enzymes involved in fatty acid biosynthesis, TAG biosynthesis, cholesterol esterification like Fasn, Dgat1, Dgat2, Mgat1, Acat1, Acat2, etc., showed a temporal increase in expression levels at the later time points post-infection." (PMID 41358489, 2025). "The data indicated that in microglia, Acat1/Soat1 is significantly elevated in many neurodegenerative diseases, including several AD mouse models (in both AβPP and tau models), acute inflammation/infection mouse models, and a mouse model for aging (22 months of age)." (PMID 36982689, 2023). "However, 25HC was unable to protect ACAT1 KO mice from Lm-InlAm infection (bottom row)." (PMID 36695568, 2023). "Our results demonstrated that the infection of BCG inhibited the expression of ABC-transporters and ACAT1 in primary bovine AMs and murine RAW264.7 cells, which in turn reduced the intracellular free cholesterol and increased cholesterol ester." (PMID 32397995, 2020). "Furthermore, similar to wild-type MH-S cells, infection of acat-1-/- cells with wild-type C. burnetii showed increased LD numbers compared to mock-infected and dotA mutant-infected cells with an average of more than 75 LDs/cell at 1, 2 and 4 days after C. burnetii infection." (PMID 29390006, 2018). "Of interest, the least ABCA1 and ACAT1 proteins in BCG-infected bovine AMs were observed at post infection 6 h, while the ABCG1 was at 12 h, and the least ABCA5 and ABCA6 were at 24 h post infection." (PMID 32397995, 2020). "ACAT-1 protein expression in the infected group increased slightly at 6 h after infection compared to that in the non-infected vehicle control, but the difference was not significant." (PMID 25299393, 2014). "Infection of cells overexpressing wild-type ACAT2, but not ACAT1, resulted in a significant increase in viral RNA and infectious particles." (PMID 37134108, 2023).
infection (continued). "ACAT1 catalyzes the last step of fatty acid beta-oxidation in the mitochondria, and its levels are induced by HCMV54, although its role during infection has not been yet investigated." (PMID 32041945, 2020).
neurodegenerative disease (6 papers, 2018 to 2024). A disorder of the central nervous system characterized by gradual and progressive loss of neural tissue and neurologic function. "Microglial Acat1/Soat1 expression is elevated in many neurodegenerative diseases and in acute neuroinflammation." (PMID 36982689, 2023). "Additionally, in a mouse model, genetic inactivation of ACAT1/SOAT1 was recently shown to benefit a rare pediatric neurodegenerative disease, Niemann-Pick type C1 (NPC1)." (PMID 36982602, 2023). "We speculate that blocking ACAT1 may increase the cholesterol content at the lipid raft domain in various membrane organelles, and it maybe through the cholesterol rich lipid raft domain that F12511 and nanoparticles alone act synergistically to benefit AD and other neurodegenerative diseases." (PMID 37446191, 2023).
metabolic disorder (3 papers, 2020 to 2025). "Second, the selective depletion of polyunsaturated CE (22:2) species despite ACAT1/SOAT1 upregulation suggests a membrane quality control mechanism that may be compromised in metabolic diseases." (PMID 40806239, 2025).
cardiovascular disease (2 papers, 2024 to 2025). "ACAT1 inhibitors previously shown to modulate cardiovascular diseases are now being implicated in immunotherapy." (PMID 38534399, 2024). "However research in models of Alzheimer’s and cardiovascular disease has shown that excessive CE formation leads to the activation of myeloid cells and subsequently to cellular damage and that this can be blocked by inhibiting ACAT1/SOAT1 activity." (PMID 40603564, 2025).
psychiatric disorder (1 paper, 2018). A disorder characterized by behavioral and/or psychological abnormalities, often accompanied by physical symptoms. "A number of the identified genes such as ACAT1 and SGIP1 confer risk for diseases or endophenotypes that are predominantly specific to the human species, such as complex psychiatric disorders." (PMID 30373661, 2018).
ACAT1 also shares sentences with these, for which no sentence is quoted: acute myeloid leukemia (2 papers); scrapie (2); acute myocardial infarction (1); adrenocortical carcinoma (1); Atrophy (1); benign tumors (1); cholangiocarcinoma (1); cocaine addiction (1); depression (1); diabetic retinopathy (1); diffuse large B-cell lymphoma (1); endometriosis (1); epilepsy (1); esophageal cancer (1); genetic disorder (1); head and neck cancer (1); hepatitis B (1); hereditary metabolic disorder (1); Hypertension (1); hyperthyroidism (1); hypertriglyceridemia (1); Hypoglycemia (1); idiopathic dilated cardiomyopathy (1); Infertility (1); kidney cancer (1); Listeria infection (1); liver disease (1); lymphocytic leukemia (1); microencephaly (1); mitochondrial disease (1).
A further 19 diseases each share a sentence with ACAT1 in 1 paper.